RPS6KA2 (ribosomal protein S6 kinase A2)
Diseases named in the same sentence as RPS6KA2 in open-access papers (continued):
Sharing a sentence is not in itself a finding about the gene and the disease.
dental caries (1 paper, 2012). The decay of a tooth, in which it becomes softened, discolored, and/or porous. "In general, we identified several suggestive loci (P-value ≤ 10E-05) within or near genes with plausible biological roles for dental caries, including RPS6KA2 and PTK2B, involved in p38-depenedent MAPK signaling, and RHOU and FZD1, involved in the Wnt signaling cascade." (PMID 23259602, 2012).
Insulin resistance (1 paper, 2023). Increased resistance towards insulin, that is, diminished effectiveness of insulin in reducing blood glucose levels. "Moreover, relevant pathways related to type I diabetes mellitus (PTPRN2), insulin resistance (RPS6KA2), and insulin secretion (ADCYAP1R1) were also identified." (PMID 37415231, 2023).
liver fibrosis (1 paper, 2025). "Furthermore, the miR‐371‐373 cluster within EXOs from intestinal cells might alleviate liver fibrosis by promoting the hepatic differentiation of HPCs via RPS6KA2 and its interaction with CREB2 and HNF4A." (PMID 40619613, 2025).
type 1 diabetes mellitus (1 paper, 2023). A chronic condition characterized by minimal or absent production of insulin by the pancreas. "Finally, our enrichment analysis identified within our DMPs, relevant pathways related to type I diabetes mellitus (PTPRN2) insulin resistance (RPS6KA2) and secretion (ADCYAP1R1)." (PMID 37415231, 2023).
tumor (30 papers, 2008 to 2025). "Interestingly, some of them were affecting cancer-related genes, i.e. a missense mutation in TFE3, a stop-gain mutation in KMT2C and a stop-gain mutation in the putative tumour suppressor gene RPS6KA2." (PMID 28420412, 2017). "These 19 de novo variants were present in non-coding regions including those of tumor associated genes ATR, RPS6KA2, IRF3, and CHD3 22–26." (PMID 34011996, 2021). "Notably, co-treatment with the miR-512-3p inhibitor, RPS6KA2 plasmid, and cisplatin led to even greater reductions in both gene expression and tumor volume." (PMID 41502518, 2025). "Notably, there was a significant positive association between KIF21A and PIGH with activated NK cells, which are immune cells with broad-spectrum anti-tumor effects, while RPS6KA2 was negatively correlated with its activation." (PMID 40098701, 2025). "Given that RPS6KA2 is localized primarily within endothelial cells, RPS6KA2 may play a role in transforming tumor-derived endothelial cells into cancer cells and promoting vascularization." (PMID 40098701, 2025). "Second, overexpression of RPS6KA2 could inhibit cell proliferation in vitro, and markedly suppressed tumor growth in vivo." (PMID 36741009, 2023). "Additionally, RPS6KA2 facilitated ferroptosis, contributing to its tumor-suppressive function." (PMID 41502518, 2025). "The results indicated that RPS6KA2 levels are inversely correlated with tumor cell proliferation and positively associated with apoptotic activity, supporting the hypothesis that RPS6KA2 may function to suppress tumor growth by inhibiting proliferation and enhancing apoptosis." (PMID 41502518, 2025). "In tumor cell lines, the reduced or absent expression of RPS6KA2 is associated with decreased apoptosis and increased proliferation, supporting earlier studies on the significance of RPS6KA2 for cellular growth, survival, and differentiation." (PMID 33980294, 2021). "In contrast, administration of the RPS6KA2 overexpression plasmid together with cisplatin reduced the expression of ATG5, ATG7, and BECN1 and inhibited tumor expansion." (PMID 41502518, 2025). "Thus, RPS6KA2 may be essential for multiple vital steps in tumor development." (PMID 40098701, 2025). "We found that the tumor volume and weight were inhibited with the overexpression of RPS6KA2 in OVCAR3 group and promoted with the knockdown of RPS6KA2 in SKOV3 group." (PMID 36741009, 2023). "We found that MAP2K6, MAP3K5, MAP3K9, MAP3K12, RPS6KA2, RPS6KA5, and STAT1 were lowly expressed in tumor tissues; However, NFKB1, RAC1, SHC1, and TRAF2 are highly expressed compared to normal tissues." (PMID 36969076, 2023). "Among the top five growth-suppressing genes tested, STARD8 and DUSP6, a commonly known tumor suppressor, arrested cells in G1/G0-phase, while MAPRE3, RPS6KA2 and EMD induced apoptosis." (PMID 28423600, 2017).
cancer (29 papers, 2012 to 2025). A tumor composed of atypical neoplastic, often pleomorphic cells that invade other tissues. "Intriguingly, such elevated RPS6KA2 levels have been associated with fortified drug resistance and the reversal of cancer cell apoptosis typically induced by chemotherapy." (PMID 40098701, 2025). "Third, evening chronotype has been associated with DNA methylation of certain gene sites, like BACH2, JRK and RPS6KA2, which are related to the cancer development." (PMID 36093575, 2023). "Several kinases associated with cancer cell survival, including KS6A2/RPS6KA2 and PLK2, are also amongst this gene set." (PMID 34359681, 2021). "The expression of JUND and RPS6KA2 is tightly and positively correlated in various cancer types." (PMID 31937753, 2020). "Among the ten genes, five of the TSGs (ATM, APC, BRCA2, NF1, and PTEN) were annotated with positive effects on apoptosis; the other three TSGs (PEG3, SPARC, and RPS6KA2) were also reported to increase apoptosis in sporadic epithelial OVC or other types of cancer." (PMID 22952919, 2012). "The target genes (MAPK8, RPS6KA2) of Lnc_002363 and Lnc_003503 were significantly enriched in the MAPK signaling pathway; this pathway is related to embryonic development, cell proliferation, division, inflammation, cancer and so on65,66." (PMID 32868811, 2020).
RPS6KA2 also shares sentences with these, for which no sentence is quoted: joint diseases (2 papers); ovarian tumor (2); Parkinson disease (2); acute myeloid leukemia (1); asthma (1); breast adenocarcinoma (1); breast tumors (1); cardiac hypertrophy (1); colorectal adenoma (1); diabetic neuropathy (1); endothelial dysfunction (1); heart failure (1); hepatocellular carcinoma (1); Hyperglycemia (1); infection (1); infertile (1); leukemia (1); osteoporosis (1); papilloma (1); small cell lung carcinoma (1); Stroke (1); triple-negative breast carcinoma (1); type 2 diabetes (1); ulcerative colitis (1).